FOXP3 (forkhead box P3)
Diseases named in the same sentence as FOXP3 in open-access papers (continued):
Sharing a sentence is not in itself a finding about the gene and the disease.
Allergy (continued). "Children with allergies had a lower number of PPG-stimulated CD4+CD25+FOXP3+T cells (P = 0.01), reduced FOXP3 expression in response to PPG and LPA (P = 0.02 and P = 0.01, respectively), and lower IL-10 production (P = 0.016), compared to the children without allergies." (PMID 27646403, 2016). "For example, on the one hand, FoxP3+ Treg do not appear to be involved in allergy regulation that occurs in healthy individuals." (PMID 24086630, 2013). "Therefore, we induced airway allergic disease in Foxp3gfp.KI mice and sorted CD4+ T cells expressing Foxp3-GFP+ Treg cells and CD4+GFP− T cells (Foxp3−) present in the lungs." (PMID 22162718, 2012). "Both FOXP3+CD4+CD25+ regulatory T (Treg) cells and inducible IL-10- and TGF-β-producing type 1 Treg (Tr1) cells may prevent the development of allergic diseases and play a role in successful allergen-SIT and healthy immune response via several mechanisms." (PMID 22409879, 2012). "Measurement of Foxp3+CD4+ cells has the potential to aid in evaluating the presence of active inflammation, which cannot be evaluated by known Th1- and Th2-related markers in patients with allergic diseases." (PMID 23283296, 2008). "However, the functional role of IL-4Rα signaling on FoxP3+ Tregs during allergic disease is not yet completely clear." (PMID 32931477, 2020). "However, directly targeting FoxP3 and acting on all FoxP3‐expressing Treg cells without discrimination might be harmful, especially by promoting allergy and auto‐immunity." (PMID 28621034, 2017). "At the age of 18 months, the expression of FOXP3, GATA-3, and CTLA-4 in Tregs was higher in the children with allergen-specific IgE sensitization without signs of clinical allergy when compared to the children who did not develop clinical allergies." (PMID 31749800, 2019). "Both PPG/LPA-stimulated FOXP3, and PPG-stimulated LAG3, gene expression levels were lower in the neonates with maternal allergies than in the neonates from mothers without allergies (P < 0.05)." (PMID 27646403, 2016). "IL-10 levels in the PPG-TLR2 innate immune pathway were lower in the offspring from the mothers with allergies than those from the mothers without allergies (P = 0.006), in agreement with the observations in CD4+CD25+FOXP3+T cells and the FOXP3/LGA3 expression profiles for these groups." (PMID 27646403, 2016).
lung carcinoma (117 papers, 2009 to 2026). "PDIA3 mutations have implications in lung cancer via abnormal immunosurveillance, while FOXP3 acts as a co‐activator in NSCLC, promoting Wnt/β‐catenin signaling, epithelial‐mesenchymal transition, and metastasis." (PMID 39945555, 2025). "A meta-analysis demonstrated that the presence of CD8+ cytotoxic T cells, CD20+ B cells, natural killer (NK) cells, and FOXP3+ Tregs is significantly associated with improved survival in early-stage lung cancer." (PMID 40723259, 2025). "The T allele in rs3761549 (T/C) FOXP3 was correlated with a susceptibility to lung carcinoma among the Iran population, whereas the A allele of rs3761548 significantly increased the NSCLC risk (OR = 2.32 and 95% CI = 1.736–3.102) in Chinese patients." (PMID 38674427, 2024). "The association between the presence of FOXP3+ CD4+ T cells in TILs has been extensively studied in all subtypes of lung cancer." (PMID 38674427, 2024). "It was indicated that the high infiltration of FOXP3+ TILs in the TME is associated with an unfavorable prognosis in lung cancer." (PMID 38674427, 2024). "For lung cancer, there are only a few reports showing that the density of Foxp3 + TILs is associated with poor prognosis." (PMID 38402536, 2024). "Here, we review recent progress in understanding the FOXP3 role in the immunogenetic architecture of lung cancer, which is the leading cause of cancer-related death." (PMID 38674427, 2024). "FOXP3 is predominantly associated with regulatory T cells, and its expression in lung cancer is often linked to the presence of tumor-infiltrating Tregs." (PMID 38674427, 2024). "Identified polymorphisms in immune checkpoints and FOXP3 associated with lung cancer development or suppression." (PMID 38983267, 2024). "This study was designed to explore the relationship between increase in CD4+CD25+FOXP3+ Treg and the higher risk of lung cancer in the elderly." (PMID 28253320, 2017). "We measured the proportion of CD4+CD25+FOXP3+ Treg and the expression level of FOXP3 mRNA in peripheral blood to explore the underlying interaction among age, Treg and lung cancer susceptibility." (PMID 28253320, 2017). "As a hallmark characteristic, the expression of Foxp3 in Treg was detected in lung cancer patients during perioperative period." (PMID 28178645, 2017). "IL-17+FoxP3+ T cells have been implicated in autoimmune disease and solid cancer development, including inflammatory bowel disease and esophageal, colon and lung cancers." (PMID 27784305, 2016). "Conversely, RFA reportedly causes a decrease in circulating CD4+ CD25+ Foxp3+ immunosuppressive regulatory T cells (Treg) 30 days post treatment in lung cancer patients which is noteworthy since Treg counteract the function of cytotoxic CD8+ effector T cells." (PMID 26599402, 2015). "FoxP3+ is a marker of regulatory T cells, a subset of TILs thought to play a major role in hampering antitumor immune response, and to represent a major cellular mechanism underlying immune evasion of lung cancer." (PMID 26871598, 2016). "A comparison of tumor-associated Treg in the KRasLA2 model of lung cancer was performed to assess whether the induction of Foxp3+ cells was a general feature of K-Ras driven lung tumorigenesis or specific for NNK-induced tumors." (PMID 19330036, 2009). "Tobacco carcinogen exposure increased pulmonary FoxP3+ lymphocytes prior to tumor development, suggesting a potential role for Tregs in the generation of a favorable niche for the development of lung tumors driven by Kras, mutations mainly found in smoker-related lung cancers." (PMID 27784305, 2016). "The expression of FOXP3/CD3 increased with the progression of lung cancer pathological staging, with mean values of 0.46 ± 0.35 in stage I, 0.26 ± 0.13 in stage II, and 0.48 ± 0.26 in stage III." (PMID 41375087, 2025). "Six key immune genes (TLR2, TLR4, CCR7, IL18, TIRAP and FOXP3) showed cell‐type specific expression patterns in the lung cancer microenvironment." (PMID 41319095, 2025).
lung carcinoma (continued). "Our analysis identified six key immune regulatory genes (TLR2, TLR4, CCR7, IL18, TIRAP and FOXP3) that show differential expression between lung cancer and normal tissues and demonstrate potential prognostic value." (PMID 41319095, 2025). "While prior studies have investigated FOXP3 and PD-1 in the context of lung cancer, the role of CD32B remains underexplored." (PMID 41375087, 2025). "Research has found that FOXP3, although as a marker for T cells, is rarely expressed in healthy cell tissues but is aberrantly upregulated in various malignant tumors, such as lung cancer, pancreatic cancer, thyroid cancer, and T-cell lymphoma." (PMID 40587482, 2025). "In lung cancer, there are only a few reports showing Foxp3 + TILs as an unfavorable prognostic factor, and they have focused mainly on adenocarcinoma." (PMID 38402536, 2024). "We have previously reported that intratumoral Tregs from lung cancer patients had significantly enhanced suppressive function and ongoing high turnover of FOXP3." (PMID 39234236, 2024). "FOXP3, a significant regulatory factor for regulatory T cells, is frequently found to be aberrantly expressed in lung cancer cells." (PMID 39372398, 2024). "The high frequency of positive SMAD3 phosphorylation in Foxp3-regulatory T cells near CD8+ T cells within the tumour identifies a rapidly progressive lung cancer patient population." (PMID 37685308, 2023). "In vitro studies have shown that CUR (10 μ M for 4 days) induces the maturation of lung cancer patient‐isolated regulatory cells (Treg) to T helper (Th)‐1 cells by inhibiting DNA transcription of forkhead protein‐3 (Foxp3) and increasing expression of IFN‐γ." (PMID 37697969, 2023). "Foxp3 was also associated with upregulation of MMP2 and MMP9 in cholangiocarcinoma cells and lung cancer cells, EMT, and metastasis." (PMID 37766222, 2023). "Our results are consistent with the findings of Sharma, Baratelli, and colleagues that PGE2 induces Foxp3 expression and Treg function in human lymphocytes and in lung cancer." (PMID 35260536, 2022). "The histological positioning of FOXP3 in nonsmall cell lung cancer (NSCLC) and its biological significance are still unclear." (PMID 36550816, 2022). "A recent pan-cancer meta-analysis determined that lung cancer patients with higher tumor densities of FoxP3+ Tregs had significantly poorer disease-free survival rates." (PMID 34141625, 2021). "A lung cancer-specific meta-analysis similarly found that, in a combined cohort of 1,303 NSCLC patients across 11 studies, an increase in tumor-infiltrating FoxP3+ Tregs was associated with poor overall survival." (PMID 34141625, 2021). "CD4+ Th1 cells, activated CD8+ T cells, and γδ-T cells were proved to be related to favorable prognosis of lung cancer, whereas Th2, Th17, and Foxp3+ Treg cells were proved to be related to an unfavorable prognosis of lung cancer." (PMID 34887858, 2021). "The density of CD4-positive (CD4+) T-cells, CD8-positive T-cells, and CD4+ Foxp3-positive T-cells were statistically higher in both tumor and stromal areas in primary lung cancer specimens when compared with brain metastases samples (p < 0.0001)." (PMID 34647108, 2021). "Evidences of this dual role include the down-regulation of MYC and HER2 by FOXP3+ Tregs, and the up-regulation of FOXP3 protein in both Tregs and tumor cells in patients with lung cancer and hepatocellular carcinoma." (PMID 30782783, 2019). "Over the past decade, the increase of regulatory CD4+CD25+Foxp3+ Treg cells has been noticed in tumor-infiltrating lymphocytes from ovarian cancer and lung cancer." (PMID 31796037, 2019). "Lung cancers with increased FoxP3+ T regulatory cells or increased MCs had worse OS, and cancers with increased CD68+ macrophages had worse DFS." (PMID 31903172, 2019). "Of note, the CD8+FoxP3+ T-cell subset was the only subset able to produce IFNγ after co-culture with autologous lung cancer cells." (PMID 30755279, 2019).
lung carcinoma (continued). "DC-based HHP lung cancer vaccine decreased the number of CD4+CD25+Foxp3+ T regulatory cells and stimulated IFN-γ-producing tumor antigen-specific CD4+ and CD8+ T cells from non-small cell lung cancer (NSCLC) patients." (PMID 28187172, 2017). "To test this possibility, we analyzed the percentage of GARP+ cells within the Foxp3+ Tregs from 39 tumor tissues and 50 PBs in lung cancer patients." (PMID 28261204, 2017). "The accumulation of CD4+CD25+FOXP3+ Treg with age correlates well with the increasing incidence of lung cancer in the elderly." (PMID 28253320, 2017). "Our experiment confirmed that, within the same age group, the proportion of CD4+CD25+FOXP3+/CD4+ T cells and the expression level of FOXP3 mRNA in the peripheral blood were significantly higher in lung cancer patients than in healthy controls." (PMID 28253320, 2017). "These indicated that GARP expression remained in a low level in Foxp3+ Tregs both from lung cancer patients and healthy donors." (PMID 28261204, 2017). "Next we addressed the number of CD4+CD25+Foxp3+ T regulatory cells induced by DC-based HHP lung cancer vaccine after 7 days." (PMID 28187172, 2017). "We compared the GARP expression in Foxp3+ Tregs between tumor tissues and PBs in lung cancer patients." (PMID 28261204, 2017). "Meanwhile, lung cancer patients had a higher concentration of CD4+CD25+Foxp3+ cells (Treg) in PBMCs." (PMID 28178645, 2017). "Forkhead box protein 3 (Foxp3) are crucial in the immunosuppressive activity of suppressor T cells or Tregs within the lung cancer tumor microenvironment (TME)." (PMID 28434399, 2017). "We first assayed the expression of GARP in Foxp3+ Tregs and Foxp3− Tconvs from 39 tumor tissues in lung cancer patients by flowcytometry." (PMID 28261204, 2017). "CD4+CD25+Foxp3+ Tregs with immunosuppressive capacity are enriched in lung cancer tumor-infiltrating lymphocytes." (PMID 28472762, 2017). "In contrast, we detected GARP expression in Foxp3+ Tregs and Foxp3− Tconvs from 50 PBs in lung cancer patients and 10 PBs in healthy donors." (PMID 28261204, 2017). "This study aimed to explore the relationship between age, increase in CD4+CD25+FOXP3+ Treg and the high incidence of lung cancer in the elderly." (PMID 28253320, 2017). "The elderly lung cancer group displayed the highest expression level of FOXP3 mRNA (3.14 ± 1.30), suggesting that FOXP3 mRNA increases with both age and lung cancer." (PMID 28253320, 2017). "CD8+CD28− TREG were found to express higher levels of FoxP3 mRNA in patients with lung cancer, suggesting the existence of a regulatory CD8+CD28− population in cancer patients, possibly regulated by the expression of FoxP3." (PMID 27314056, 2016). "In a study looking at T cells from blood and TIL from lung cancer patients, freshly isolated γδTc only slightly expressed FoxP3 compared to CD4+ T cell TIL, of which almost half were positive for this regulatory marker." (PMID 25477885, 2014). "Using carcinogen, allograft and transgenic models of lung cancer driven by K-Ras, we have shown that Foxp3+ cells are essential for lung tumorigenesis." (PMID 19330036, 2009). "Additionally, in gastric and lung cancers, the CD8 to Foxp3 relationship is associated with ICI therapy effectiveness." (PMID 40274705, 2025). "TSLP was overexpressed in intratumoral lung cancer and correlated with Foxp3+ Tregs." (PMID 40873585, 2025). "In addition, it is noteworthy that FOXP3-expressing Tregs play a crucial role in modulating the immune response in lung cancer, promoting tumor immune evasion and contributing to disease progression." (PMID 38674427, 2024). "More evidence has recently emerged revealing the carcinogenic effects of FOXP3 in lung cancer." (PMID 38674427, 2024). "Notably that those samples, although downregulated their Treg numbers, appeared to be less sensitive to the effect of ASO FOXP3 in comparison with distant tumor-free lung cancer samples and in comparison with other cancer samples." (PMID 39234236, 2024).
lung carcinoma (continued). "In this review, we summarize the recent data regarding FOXP3 expression in lung cancer cells, spatial architecture of tumor-infiltrating FOXP3+ T cells, prognostic significance of FOXP3+ TILs, FOXP3 impact on lung cancer stemness and FOXP3+ TILs in the context of cancer therapy." (PMID 38674427, 2024). "In addition, the authors confirmed that the enhancement of lung cancer stemness by FOXP3 was partially stimulated via Notch1." (PMID 38674427, 2024). "Recent studies have increasingly underscored the oncogenic role of FOXP3 in lung cancer." (PMID 39372398, 2024). "In the NSCLC group, FOXP3 is highly expressed in lung squamous cell carcinoma (p < 0.001) and lung adenocarcinoma (p < 0.001), suggesting that this gene plays a role as an oncogene in lung cancer." (PMID 38674427, 2024). "Kadota30 found that TB in lung cancer was relevant to stromal TILs, especially FoxP3+ lymphocyte, which is a kind of regulatory T-lymphocytes, and may exert immunosuppression in tumor microenvironment." (PMID 37678011, 2023). "The percentage of CD137+ regulatory T cells (Tregs) in the blood of lung cancer patients was also increased, and further enriched at the tumor site; Foxp3, CTLA-4, IL-10, IL-35-Ebi3, sCD137 and costimulatory molecules expression were also higher, indicating increased immunosuppressive activity." (PMID 35197968, 2022). "Moreover, accumulation of CD4+FOXP3+ Tregs was reported to correlate with increasing incidence of lung cancer." (PMID 35688943, 2022). "For example, identified immunostimulatory factors (e.g. IFNG in lung cancer) are associated with a negative prognosis, whereas immunosuppressive factors (e.g. FOXP3/IL10 in ovarian cancer) are associated with a positive prognosis." (PMID 36419893, 2022). "In lung cancer, for example, high levels of CD8+ (=cytotoxic) tumor-infiltrating lymphocytes (TILs) seem to have a positive prognostic effect, whereas high levels of FoxP3+ regulating TILs are associated with a poorer prognosis." (PMID 35158964, 2022). "Interestingly, the number of Foxp3+ Tregs in lung cancer tissue was significantly increased compared to peritumoral lung tissue." (PMID 34440780, 2021). "For instance, in lung cancer, the “mesenchymal” phenotype is associated with distinct TME changes, including the elevation of immune checkpoint molecules and the enhanced tumor infiltration by CD4+Foxp3+ regulatory T cells and CD3+ T cells." (PMID 34277389, 2021). "Although a BETi (JQ1) is proved to attenuate CD4+FOXP3+ Treg cell suppressive function in lung cancer therapy, how BET family proteins associate with FOXP3-promoting Treg cell functions is still unknown." (PMID 34072421, 2021). "An intriguing finding of our studies was that MTR OralGem treatment enhanced antitumor immunity in a syngeneic lung cancer model by decreasing the percentages of CD4+Foxp3+ Treg cells and increasing CD3+CD4+ and CD3+CD8+ T effector cell infiltration in the TME." (PMID 33920884, 2021). "Increased level of FOXP3 is shown to enhance the viability and invasiveness of tumors in NSCLCs, thus Treg can be yet another link in immunity which lung cancer might exploit to promote its growth." (PMID 33262947, 2020). "Similarly, we found a statistically significant increase in CD4+CD25+FoxP3+ frequency in MPEs over the course of lung cancer, with the highest Treg percentage in MPEs with malignant cells." (PMID 29785404, 2018). "Thus, GARP was mainly expressed in tumor-infiltrating Foxp3+ Tregs instead of that from lung cancer patients PBs." (PMID 28261204, 2017). "Comparison of CD4+CD25+FOXP3+/CD4+ T cells in lung cancer patients." (PMID 28253320, 2017). "In conclusion, although some papers address the role in CD8 and Foxp3 in lung cancer, the original aspects of this study lies in the fact that the tumor and stroma compartment of the tumor tissue have been investigated separately with a double approach using IHC and RTqPCR." (PMID 27463005, 2016).